ALB (albumin)
Diseases named in the same sentence as ALB in open-access papers (continued):
Sharing a sentence is not in itself a finding about the gene and the disease.
COVID-19 (continued). "According to the order of area under ROC curve from large to small, these early predictors were the severe COVID-19 risk model (0.920), albumin (0.867), NLR (0.835), lymphocyte count (0.826), and age (0.747), successively." (PMID 33110593, 2020). "The components of the PNI (serum level of albumin, and lymphocyte count) were strongly associated with critical illness due to COVID-19." (PMID 33521032, 2020). "Before adjustment, eight factors were in statistically significant association with the risk of severe or critical COVID-19 when compared with mild or ordinary COVID-19 (p <0.05), including diagnostic delay, ALB, LDH, WBC, HGB, LYMPH, MONO, and NEUT." (PMID 33318316, 2020). "Decreased albumin at admission has been an independent risk factor associated with unimprovement during follow-up in COVID-19 patients." (PMID 33224959, 2020). "Studies have confirmed that decreases in albumin and albumin globulin ratios were risk factors for the prognosis of cancer patients with COVID-19." (PMID 33232275, 2020). "Nutritional risk was associated with severe COVID-19 (p < 0.01; p < 0.01 after adjustment for C reactive protein), as were lower plasma proteins, albumin, prealbumin, and zinc levels (p < 0.01)." (PMID 33260603, 2020). "Overall, we found that lower albumin levels were associated with longer hospital length and mortality (r = –0.472, p < 0.001 and r = −0.424, p = 0.003, respectively) in COVID-19 patients." (PMID 32722020, 2020). "Recent observational studies on patients with COVID-19 have demonstrated that a reduced albumin concentration in serum is associated with increased disease severity." (PMID 33521032, 2020). "The observed correlations between histatin-3 and ferritin, D-dimer, and albumin further suggest that histatin-3 may be linked to acute-phase and inflammatory responses during COVID-19." (PMID 42267407, 2026). "Device caps (Prismaflex ≤ 1000 mL/h loss; HF404 ≤ 500 mL/h), replacement fluid choice (FFP vs. albumin), and COVID-19 disease severity may each influence iCa and hemodynamics." (PMID 41148770, 2025). "Our findings highlight that children with higher levels of inflammation markers, particularly a higher NLR and lower serum albumin levels on admission may be more prone to develop COVID-19-associated AKI." (PMID 39031240, 2024). "It has been reported that exposure to nephrotoxic drugs, high C-reactive protein (CRP), increased white blood cell (WBC) counts, and low serum albumin levels may be risk factors for AKI in children with COVID-19." (PMID 39031240, 2024). "Furthermore, high concentrations of lactate dehydrogenase and low concentrations of albumin in serum are linked to higher mortality in COVID-19 patients." (PMID 38576552, 2024). "In conclusion, impaired gut barrier permeability, increased NOX2 activation, and low serum albumin may account for low-grade endotoxemia and may be implicated in thrombotic events in COVID-19." (PMID 39456513, 2024). "Notably, genetic liability to higher albumin was linked to a reduced risk of severe COVID-19, with an odds ratio (OR) of 0.96 for each SD increase in albumin (95% CI: 0.93–1.00)." (PMID 38549094, 2024). "Thus, the additive effect of both albumin and globulin will not only be a prognostic factor for possible complications of COVID-19 during the course of the disease but also an initial risk index for SARS-CoV-2-positive individuals." (PMID 38611597, 2024). "Our results also demonstrated that serum albumin level may serve as a novel and simple early biomarker to identify COVID-19 patients at high risk for mortality." (PMID 38639116, 2024). "Increased C-reactive protein, combined with increased serum lactate and a high lactate/albumin ratio, may assist clinicians in identifying COVID-19 patients at risk of mechanical ventilation and mortality upon admission." (PMID 38576552, 2024).
COVID-19 (continued). "Their genomic admixture with modern humans has been linked to multiple physiological features and disease susceptibility in modern humans, including pigmentation, immunity, metabolism, cognition traits, coronary artery disease and albumin/globulin ratio, and COVID-19 susceptibility." (PMID 38287404, 2024). "Indeed, severe COVID-19 has been associated with immunological and vascular changes, as well as alterations in many acute phase proteins including albumin." (PMID 39685564, 2024). "It is assumed that hypoalbuminemia in COVID-19 develops not only due to the damage to the hepatocellular system but also as a result of systemic inflammation and increased capillary permeability, which causes albumin to disappear into the interstitium." (PMID 37109161, 2023). "Moreover, some studies have linked higher albumin levels and lower globulin levels with a favorable prognosis for COVID-19." (PMID 37515140, 2023). "In the present study, we observed that the relative abundance of Lactobacillus was dominant in severe patients and negatively correlated with albumin levels in patients with COVID-19; this suggests that Lactobacillus is associated with liver function maintenance." (PMID 38149007, 2023). "A comparative analysis of the esterase status of apparently healthy elderly subjects and patients of the same age with COVID-19 at the final stage of our multifaceted study allowed us to obtain additional evidence of the importance of albumin as a diagnostic marker." (PMID 37373530, 2023). "The association between P/F ratio and albumin is another novel finding that may provide new insight into the relationship between P/F ratio and thrombosis in COVID-19." (PMID 36650311, 2023). "Our secondary objective was to describe trajectories of FeNa, FeUrea, FeUA, urinary protein-to-creatinine ratio (UPCR) and urinary albumin-to-creatinine ratio (UACR) using twice weekly measurements during hospitalization to gain a better insight into the pathogenesis of COVID-19-associated AKI." (PMID 36127479, 2023). "In addition, this study found a significant decrease in albumin levels in the severe group, which is consistent with findings in cases of Delta variant-associated COVID-19." (PMID 38145047, 2023). "Serum albumin levels have been linked to poor outcomes in patients with COVID-19." (PMID 37448768, 2023). "In this study, we unraveled that older age and higher levels of laboratory test indexes such as CRP, LDH, and glucose, and lower levels of laboratory findings such as lymphocytes and albumin on admission were associated with higher probabilities of critical illness COVID-19." (PMID 35677769, 2022). "MB, TLR4 and ALB are involved in coronavirus biology, and are associated with COVID-19 prognosis." (PMID 36275701, 2022). "A survival analysis revealed that comorbidities, lymphocyte counts, platelet count, serum albumin, C-reactive protein level, and renal dysfunction may be risk factors in patients with COVID-19." (PMID 33762058, 2022). "As already mentioned, although albumin has been considered a predictor for hospitalized patients with severe disease, surprisingly, the association between the mortality risk of patients hospitalized for COVID-19 and the function of serum albumin levels has only been evaluated in a very limited way." (PMID 35160039, 2022). "Numerous previous studies suggested that serum albumin could be used as an early prognosis biomarker, by displaying that serum albumin levels were abnormally low in COVID-19 patients, and, thus, were associated with the severity of the disease." (PMID 35736249, 2022). "Still, it should be noted that for our patients, many laboratory features were strongly associated with a worse prognosis of COVID-19, such as low hemoglobin levels, low platelet counts, low albumin levels, elevated liver enzyme levels, prolonged prothrombin time, and elevated LDH levels." (PMID 35475059, 2022).
COVID-19 (continued). "These complications may be associated with liver dysfunction in the production of albumin, acute reactants, and coagulation factors, leading to multi-system manifestations of COVID-19, such as ARDS, coagulation, and multiple organ failure." (PMID 35419371, 2022). "When the authors defined a covariate as having a confounder effect provided that the change in p-value (for association between DPP4 activity and mortality in COVID-19) was at least 1 log, then only the plasma glucose and serum albumin concentrations were identified as confounding factors." (PMID 35195023, 2022). "Albumin is produced in the liver, but it has been subject to dispute as to whether its insufficiency in COVID-19 could be caused by liver dysfunction." (PMID 35956107, 2022). "This may explain the close association observed between a lower concentration of albumin and increased disease severity and mortality in patients with COVID-19 in many studies." (PMID 36077496, 2022). "Likewise, it is likely that as albumin values are influenced by other parameters independently associated with the severity and poorer prognosis of patients with COVID-19, they contribute to the prognostic value of the AGR, for example, age." (PMID 35601226, 2022). "Finally, urinary SARS-CoV-2 N and plasma albumin levels identified patients at risk for premature death in COVID-19." (PMID 34113632, 2021). "Our findings showed that albumin, direct bilirubin, white blood cell count, neutrophil count, lymphocyte count, and mean corpuscular hemoglobin are casually associated with the risk of severe COVID-19." (PMID 34122505, 2021). "The state of chronic elevation of inflammatory markers in patients with such co-morbidities might have caused the lowering of serum albumin which is the main plasma anti-antioxidant, and hence signifying severity of COVID-19." (PMID 33930096, 2021). "In addition to the 4C mortality score, frailty score and a low albumin were strongly independently associated with 30-day mortality in two consecutive cohorts of patients admitted to hospital with COVID-19." (PMID 34043668, 2021). "Laboratory findings associated with severe COVID-19 are decreased albumin, high C reactive protein, high lactate dehydrogenase, lymphopenia, eosinopenia, high erythrocyte sedimentation rate, leucopenia or leucocytosis, hyperbilirubinemia, elevated liver enzymes and high creatinine." (PMID 32788312, 2021). "In the future, it may be possible to identify cancer patients at risk for severe/critical COVID-19 using criteria including low SpO2 and albumin as well as high hs-CRP, LDH and BUN." (PMID 33995633, 2021). "In a series of 91 consecutive COVID-19 adult patients with various comorbidities, we were able to collect a range of phenotypical (BMI, weight loss) and biological (albumin, CRP) data at the beginning of hospitalization for COVID-19 and one month after hospital discharge." (PMID 34209229, 2021). "The purpose of our study is to identify whether there is an association between initial admission albumin levels and adverse outcomes in COVID-19 patients." (PMID 33725003, 2021). "Therefore, lower serum albumin concentrations are significantly associated with disease severity and adverse outcomes in COVID-19 patients." (PMID 33511503, 2021). "Serum albumin is also associated with increased mortality in COVID-19 patients." (PMID 34683480, 2021). "In addition, combining urinary SARS-CoV-2 N and plasma albumin levels at ICU admission identified patients at risk for premature death in COVID-19 (two-variable model, HR 7.6, 95% CI 1.3–44, p = 0.0240)." (PMID 34113632, 2021). "Low serum albumin level, which is an important mortality indicator for patients followed up in intensive care units, was also found to be associated with poor prognosis in pneumonia caused by COVID-19." (PMID 34784756, 2021).
COVID-19 (continued). "We designed the present study to explore how COVID-19-caused mortality is related to oxidative stress and whether ROS-induced albumin damage can be used to predict such outcome." (PMID 34821549, 2021). "More recently, high CRP and low albumin have been associated with increased mortality in COVID-19." (PMID 34123422, 2021). "Some studies suggest that serum albumin levels may also be associated with prognosis in hospitalized patients with COVID-19." (PMID 34367693, 2021). "Although in COVID-19 patients, the risk of thrombosis may persist even after discharge from the hospital albumin serum concentration was seldom mentioned as a potential risk for thrombosis." (PMID 34281177, 2021). "Furthermore, the levels of IL-6 and albumin are independent risk factors for pulmonary fibrosis and should be regarded as important therapeutic targets for the treatment of COVID-19 patients with pulmonary fibrosis." (PMID 33755708, 2021). "Reduced serum levels of albumin are associated with poorer outcomes in patients with COVID-19." (PMID 33925831, 2021). "A simple point of care 3-item risk score that includes age, oxygen saturation, and albumin predicts with good discriminative capacity, sensitivity, and specificity whether a patient with COVID-19 is suitable for discharge." (PMID 33274414, 2021). "A 3-item risk score for patients with COVID-19 consisting of age, oxygen saturation, and an acute phase reactant (albumin) using point of care data predicts suitability for discharge and may optimize scarce resources." (PMID 33274414, 2021). "Similarly, previous reports have detected low serum albumin in patients with severe COVID-19, which was linked to thrombotic events." (PMID 34966381, 2021). "In this study, we retrospectively studied 419 patients from five hospitals in Shanghai, Hubei, and Jiangsu Provinces and determined several risk factors for the severity of COVID-19 in these patients, including age ≥60 years, ALB level, comorbidity, and CRP level." (PMID 33330318, 2020). "Normal serum albumin levels were inversely associated with death from COVID-19 in cancer patients." (PMID 32903324, 2020). "Moreover, elevated alanine aminotransferase (ALT) levels and reduced albumin levels are found to be associated with higher mortality in COVID-19, which can be caused by chronic liver and kidney diseases." (PMID 33110586, 2020). "Our study has confirmed that ALB is a risk factor for the severity of COVID-19." (PMID 33330318, 2020). "In addition, a case series study conducted in Italy also concluded that a low albumin level was a significant risk factor for mortality and protracted hospital stay among hospitalized COVID-19 patients." (PMID 33260480, 2020). "Similarly, we noted that dyspnea at presentation, high CRP levels, and low levels of albumin were associated with death from COVID-19." (PMID 32903324, 2020). "Furthermore, low levels of albumin, prealbumin, protein, and zinc, and higher levels of magnesium, were also associated with the severity of COVID-19 (p < 0.01)." (PMID 33260603, 2020). "Besides, AST, ALT and albumin were also independent risk factors for the in-hospital mortality in severe and critically ill patients with COVID-19." (PMID 32922185, 2020). "In addition, an inverse association with death from COVID-19 was observed with normal albumin levels [3rd tertile vs. 1st tertile—HR: 0.04 (95% CI: 0.01–0.04)]." (PMID 32903324, 2020). "Furthermore, the reduced production and increased loss of albumin in serum can be seen in patients with damage to liver function and renal function, which are common attributes in critically ill COVID-19 patients." (PMID 33521032, 2020). "Lower levels of albumin were associated with poorer outcomes in COVID-19 patients." (PMID 32722020, 2020). "Albumin adjusted for CRP level was still associated with severe COVID-19 (p = 0.03)." (PMID 33260603, 2020). "Low albumin levels have been associated with survival in COVID-19 patients as well." (PMID 32722020, 2020).
COVID-19 (continued). "The results showed that lymphocyte count and albumin on admission were the independent early predictors for severe COVID-19, and the severe COVID-19 risk model was constructed as following: Logit(P) = 15.779 − 2.531 × Initial lymphocyte count ( × 109/L) − 0.346 × Initial albumin (g/L)." (PMID 33110593, 2020). "A recent meta-analysis indicated that other commonly available biomarkers (such as hemoglobin and albumin) could assist risk stratification for severe and fatal COVID-19." (PMID 32756383, 2020). "We found that albumin may be an independentpredictive marker (cut-off point: 35.1 g/l) for the risk ofnonsurvivors in critically ill patients with confirmed COVID-19." (PMID 32490680, 2020). "This study bridges structural findings with an analysis of publicly available clinical data from Wuhan and suggests that an adjustment of the dexamethasone regimen should be further investigated as a strategy for patients affected by two major COVID-19 risk factors: low albumin levels and diabetes." (PMID 33063792, 2020). "In the multivariate analysis, only albumin levels below 35 g/L (odds ratio [OR]: 4.914, 95% confidence interval [CI]: 1.131–21.346, p = 0.034) and ferritin levels above 306.8 ng/mL (OR: 3.838, 95% CI: 1.096–13.433, p = 0.035) remained independent risk factors of severe COVID-19." (PMID 39928605, 2025). "Therefore, the aim of this study was to explore the interplay between NOX2, LPS, and albumin and to assess if such interplay may be implicated in the hypercoagulation state of COVID-19." (PMID 39456513, 2024). "Recent studies indicate that both a decrease in the total albumin level and an increase in the proportion of oxidized albumin are highly sensitive diagnostic markers and reliable predictors of the outcome of many common and socially significant diseases, including COVID-19." (PMID 37373530, 2023). "However, low serum levels of ALB have already been associated with poor COVID-19 patient prognosis." (PMID 36514048, 2022). "Our results revealed that D-dimers were moderate negatively correlated with albumin concentration (r = −0.477), positively associated with AOPPs level (r = 0.453), and positively associated with the AOPPs/albumin ratio (r = 0.534) in COVID-19-related pneumonia patients." (PMID 36077496, 2022). "Moreover, serum albumin may reduce the risk of severe COVID-19 by modulating on the levels of lymphocyte count or mean corpuscular hemoglobin, indicated by the data from multivariable MR." (PMID 34122505, 2021). "In conclusion, serum albumin level was shown to have a significant association with mortality in our study population and could be considered a strong predictor for mortality in hospitalized patients with COVID-19." (PMID 34367693, 2021). "Therefore, in addition to prior known biomarkers (e.g., procalcitonin, CRP, lymphocyte count, D-dimer, troponin I, AST, ALT, among others) associated with severe COVID-19, serum albumin levels might help in prognostic risk stratification." (PMID 33725003, 2021). "HF likely [Odds ratio (OR) 1.97, 95% CI 1.13–3.42], age (OR 1.04, 95% CI 1.02–1.06), lymphocyte (OR 0.36, 95% CI 0.19–0.68), albumin (OR 0.92, 95% CI 0.87–0.96), and total bilirubin (OR 1.02, 95% CI 1–1.04) were independently associated with the prognosis of critically ill patients with COVID-19." (PMID 34901205, 2021). "Accordingly, a recent meta-analysis of more than 3400 COVID-19 patients indicated a prime importance of the liver for survival, and highlighted increased mortality risk with elevated circulating liver injury markers (alanine aminotransferase, aspartate aminotransferase, albumin and bilirubin)." (PMID 34072977, 2021). "Interestingly, the levels of urinary SARS-CoV-2 N and plasma albumin did not correlate directly, suggesting that combining urinary SARS-CoV-2 N and plasma albumin could further improve risk stratification for AKI in COVID-19." (PMID 34113632, 2021).